PSMA6 (proteasome 20S subunit alpha 6)
Diseases named in the same sentence as PSMA6 in open-access papers (continued):
Sharing a sentence is not in itself a finding about the gene and the disease.
psoriasis (2 papers, 2021 to 2025). An autoimmune condition characterized by red, well-delineated plaques with silvery scales that are usually on the extensor surfaces and scalp. "Firstly, in order to establish the role of PSMA6 polymorphism in the development of psoriasis, further experimental studies are necessary." (PMID 34575036, 2021). "We made an attempt to detect possible links between the NOTCH3 (6746T>C) and PSMA6 (-8C>G) polymorphisms and psoriasis in five genetic models: dominant, recessive, additive, heterozygote, and allelic." (PMID 34575036, 2021). "The correlation of PSMA6 G allele carriers (GG + CG) and CC homozygotes with psoriasis clinical features revealed that psoriatic arthritis was more frequent among patients with the CC genotype (p = 0.059)." (PMID 34575036, 2021). "The aim of the study was to analyze the NOTCH3 (6746T>C) (rs1044009) and PSMA6 (-8C>G) (rs1048990) polymorphisms and their role in genetic susceptibility to psoriasis." (PMID 34575036, 2021). "We identified PSMA6, a reported genetic risk factor for the development of psoriasis and IBD52,53, PSMA7 (proteasome 20S subunit alpha), a biomarker of IBD54, and RPS3 (ribosome small 40S subunit) as potential LZTR1-interacting proteins, while only PSMA7 and RPS3 were validated through co-IP." (PMID 41162356, 2025). "Therefore, our study made an attempt to find a possible association between the NOTCH3 as well as PSMA6 polymorphisms and genetic susceptibility to psoriasis." (PMID 34575036, 2021). "Therefore, since psoriasis is a systemic disease, it may be surmised that the PSMA6 polymorphism plays a role in the genetic susceptibility to psoriasis." (PMID 34575036, 2021). "Our study aimed at investigating the genetic aspect of psoriasis etiology and it focused especially on the NOTCH3 and PSMA6 polymorphisms." (PMID 34575036, 2021). "The other psoriasis clinical features did not correlate with the PSMA6 polymorphism." (PMID 34575036, 2021).
chronic kidney failure (1 paper, 2016). "Our study was designed to address the potential involvement of the PSMA6 gene polymorphism for the first time in chronic kidney failure." (PMID 27671905, 2016).
colorectal cancer (1 paper, 2025). A primary or metastatic malignant neoplasm that affects the colon or rectum. "Multiple SASP-linked proteins that rose in GCR-exposed mouse serum including, PSAP, THBS1, TIMP2, CST3, and PSMA6 are broadly detected in human malignancies, including breast and colorectal cancers were upregulated after GCR exposure." (PMID 41516087, 2025). "For instance, Prosaposin (PSAP), Endoplasmic reticulum resident protein 44 (ERP44), Proteasome subunit alpha type-6 (PSMA6), and Histone H4 (HIS1H4A) were highly expressed in most of the breast and colorectal cancer samples." (PMID 41516087, 2025).
Crohn disease (1 paper, 2022). A gastrointestinal disorder characterized by chronic inflammation involving all layers of the intestinal wall, noncaseating granulomas affecting the intestinal wall and regional lymph nodes, and transmural fibrosis. "Moreover, the single-cell transcriptomic analysis showed that tuft cells may play an important role in intestinal enteritis—the enrichment of PSMA6 (Proteasome 20S subunit alpha 6, associated with Crohn’s disease risk) in tuft cells may lead to impaired epithelial integrity and stress responses." (PMID 36045190, 2022).
diabetic retinopathy (1 paper, 2024). "We explored differences in the DNA methylation statuses of PSMA6, PSMB5, HIF1A, and KEAP1 gene promoter regions in patients with type 1 diabetes and different diabetic retinopathy (DR) stages." (PMID 38927561, 2024).
ductal breast carcinoma (1 paper, 2017). "According to Perou's dataset and two analyses of Sorlie, PSMA6 was markedly elevated in ductal breast carcinoma compared to normal tissues." (PMID 27966459, 2017).
end-stage renal disease (1 paper, 2016). "Left ventricular hypertrophy (LVH) is a strong cardiovascular risk marker in end-stage renal disease patients, so we also investigated the association between PSMA6 polymorphism and LVH present in 54 % of our patients." (PMID 27671905, 2016).
glioblastoma (1 paper, 2020). The most malignant astrocytic tumor (WHO grade IV). "The radiation-induced upregulation of PSMA6 is in line with recent findings in EVs from head and neck and glioblastoma cells suggesting that this protein is radiation-regulated in a cell type-independent manner." (PMID 32230970, 2020).
Hypertension (1 paper, 2025). The presence of chronic increased pressure in the systemic arterial system. "Notably, carriers of the PSMA6 rs1048990 G allele showed an increased risk of DKD, even after adjustment for HbA1c, T1DM duration, hypertension, and presence of DR (OR = 1.747, p = 0.042)." (PMID 41441015, 2025).
kidney cancer (1 paper, 2017). Primary or metastatic malignant neoplasm involving the kidney. "Consistent with the trend seen in Oncomine, the expression levels of PSMA1-4 and PSMA6-7 were significantly increased in 889 kidney cancers compared with 129 normal tissues in the TCGA mRNA HiSeq expression data." (PMID 27966459, 2017). "Notably, although PSMA1-4 and PSMA6-7 were increased in overall kidney cancer, the transcriptional patterns of PSMAs were different among the three subtypes." (PMID 27966459, 2017). "Moreover, only PSMA6 and PSMA5 were not overexpressed in colorectal and kidney cancer, respectively." (PMID 27966459, 2017).
kidney clear cell carcinoma (1 paper, 2017). "The expression levels of PSMA1-3 and PSMA6 were higher in kidney clear cell carcinoma than in normal samples." (PMID 27966459, 2017).
neuroblastoma (1 paper, 2007). Neuroblastoma (NB) is the most common solid, extracranial childhood tumor. "In Cluster 1, transcripts are over-expressed in the mouse neuroblastoma cell lines in a tumor-restricted manner: Chgb, Dus31, 2310042G06Rik, Psma6 (proteasome subunit), Csnk2a1 (casein kinase), Mtrr (metabolic activation), and Hspa8 (heat shock protein)." (PMID 17397536, 2007).
Obesity (1 paper, 2013). Accumulation of substantial excess body fat. "An SNP frequency examination of the subjects' first-degree relatives would shed some light on these discrepancies and would seem appropriate in the future in order to clarify the specific roles played by polymorphisms at the PSMA3 and PSMA6 c.-8C>G loci in the promotion of obesity." (PMID 24455213, 2013). "We investigated the possible association of polygenic obesity with single nucleotide polymorphisms of the PSMA6 and PSMA3 proteasomal genes, based on our hypothesis that altered proteasome expression may be an important factor that can result in obesity in children." (PMID 24455213, 2013). "Since polygenic obesity is a major risk factor for T2DM and given the association between PSMA6 and T2DM, we hypothesize an association between childhood obesity and the PSMA6 gene as well as the PSMA3 proteasomal gene, which interacts with the PSMA6 gene in forming structurally linked proteasomes." (PMID 24455213, 2013).
psoriatic arthritis (1 paper, 2021). Joint inflammation associated with psoriasis. "Psoriatic arthritis was more frequent among patients with the CC genotype of PSMA6 (p = 0.059)." (PMID 34575036, 2021). "However, in our patients with psoriatic arthritis, the PSMA6 CC genotype was more frequently observed than in the carriers of G allele (38% vs. 20%)." (PMID 34575036, 2021).
renal Wilms tumor (1 paper, 2017). "In Yusenko's dataset, the transcription levels of both PSMA3 and PSMA6 were higher in renal Wilms tumor than in normal tissues." (PMID 27966459, 2017).
Stroke (1 paper, 2016). Sudden impairment of blood flow to a part of the brain due to occlusion or rupture of an artery to the brain. "There are two previous studies, reporting a decreased risk of stroke associated with the PSMA6 −8 G/C polymorphism in Caucasian populations." (PMID 27671905, 2016).
viral infection (1 paper, 2024). "In addition, the Psma6 gene present on Chr 27 has been reported as a key regulator of the immune response gene against viral infection and was also found in a hepatitis C viral infection study." (PMID 39628812, 2024).
cancer (15 papers, 2015 to 2025). A tumor composed of atypical neoplastic, often pleomorphic cells that invade other tissues. "Little is known about the role of the PSMA6 -8C>G polymorphism in cancer development, including MM." (PMID 32596371, 2020). "Pharmacological PSMA6 inhibition induces G2/M arrest or apoptosis in cancer models, while its essential role in porcine adipocyte proliferation has been established." (PMID 40507774, 2025). "Reflecting the pleiotropic functions of the vitamin D/PTH axis, other potential candidate genes were also implicated immune/inflammatory processes (NKX2, PSMA6, SNX6) as well as cancer (NKX2, NKX3, PAX9)." (PMID 27579147, 2016). "In cancer, PSMA6 is often upregulated to promote tumor progression by degrading tumor suppressors." (PMID 40507774, 2025). "In addition to MCM2 to MCM7, six downstream oncogenic targets of c-MYC implicated in cancer survival and metabolism including PSMA1, PSMA6, PSMB2, HDAC2, LDHA and SPRING were positively correlated with IFITM3 in 71 GC specimens using the Cho dataset." (PMID 35941699, 2022). "PSMA6 has also been shown to have an oncogenic role in several cancer types." (PMID 30898113, 2019).
tumor (11 papers, 2007 to 2026). "Enrichment analyses disclosed the involvement of PSMA6 in immune-related activities within the tumor microenvironment." (PMID 41799753, 2026). "Furthermore, the expression of PSMA6 was closely correlated with tumor-infiltrating immune cells (TICs) and immune checkpoints (ICPs)." (PMID 41799753, 2026). "In contrast, this study revealed that ATP6V1G1 at 9q and PSMA6 at 14q might be potential tRCC tumor suppressors." (PMID 36470859, 2022). "Therefore, [211At]PSMA5 showed better tumor-to-kidney uptake than [211At]PSMA6 did." (PMID 36344651, 2023).
heart disease (3 papers, 2016 to 2022). "In CMs, we found three genes in OMIM (Online Mendelian Inheritance in Man) with gene × treatment interactions that are known to cause Mendelian forms of heart disease: PSMA6, AARS2, DSC2." (PMID 33988505, 2021).
infection (1 paper, 2014). The state of being infected such as from the introduction of a foreign agent such as serum, vaccine, antigenic substance or organism. "The validation of a number of differentially expressed proteins showed that the expression of PKM2, HSPB1, and PSMA6 was significantly different during the infection course between the virulent HuN4 strain and the attenuated HuN4-F112 strain." (PMID 24465692, 2014). "PSMA6 was upregulated following infection with the HuN4 strain in the present study and was downregulated by infection with the HuN4-F112 strain." (PMID 24465692, 2014). "Similar to HSPB1, PSMA6 was also upregulated with HuN4 infection and downregulated when infected with HuN4-F112, and the difference at 48 hpi between them was significant (P<0.05), too." (PMID 24465692, 2014).
PSMA6 also shares sentences with these, for which no sentence is quoted: pancreatic cancer (3 papers); bladder cancer (2); ovarian carcinoma (2); Parkinson’s (2); ankylosing spondylitis (1); autoimmune disease (1); brain cancer (1); Cachexia (1); cervical cancer (1); colon cancer (1); endometrial cancer (1); head and neck cancer (1); kidney renal cancer (1); large cell lung carcinoma (1); left ventricular hypertrophy (1); liver cancer (1); lymph node metastases (1); mastitis (1); myelodysplastic syndrome (1); nasopharyngeal carcinoma (1); neurological disorders (1); type 1 diabetes (1); varicocele (1).